FGF1 (fibroblast growth factor 1)
Diseases named in the same sentence as FGF1 in open-access papers (continued):
Sharing a sentence is not in itself a finding about the gene and the disease.
cancer (continued). "The FGF1 expression level in several cancer types, such as breast cancer, hepatocellular carcinoma, and esophageal cancer, shows that growth factors promote tumor cell invasion and metastasis." (PMID 37108717, 2023). "From the top down- and up-regulated DEG, four genes (ADAMTS1, FGF1, G0S2 and TP63) were also closely associated with cancer pathways according to the literature." (PMID 35840561, 2022). "In all cases, we observed that FGF1 stimulation reduced PARP processing, demonstrating that FGF1 acts as an inhibitor of apoptosis in cancer cells treated with anticancer drugs targeting tubulin polymerization." (PMID 36276073, 2022). "Aberrant expression of FGF1 promotes the development of various human cancers, such as breast cancer, bladder cancer and hepatocellular carcinoma." (PMID 35864158, 2022). "Consistently, TCGA datasets from other types of cancers further verified the positive correlation between FGF1 and LHX2 expression." (PMID 35864158, 2022). "Both online GEPIA and Oncomine analysis indicated that although FGF1 expression various in different cancers, it was aberrant lost in ccRCC." (PMID 33865387, 2021). "The analysis result showed not only that FGF1 expresses much less in cancer comparing to normal renal tissues, but also the expression tends to decrease as the cancer grade and stage advancing although the difference was not statistical significant." (PMID 33865387, 2021). "RFX1 reduces cancer cell proliferation by targeting FGF1 and transforming growth factor beta 2 (TGFβ2), induce differentiation by targeting CD44 and c-Myc, and promote apoptosis by regulating myeloid cell leukemia sequence 1 protein (MCL1)." (PMID 33964962, 2021). "BCL2, CXCL8, and FGF1 promote cancer cell metastasis and invasion through EMT regulation in various cancers." (PMID 34199510, 2021). "What’s more, QPCR experiment performed using 30 different patients samples also validated that FGF1 expressed less in cancer comparing to matched normal tissues." (PMID 33865387, 2021). "Overexpression of fibroblast growth factor 1 (FGF1) is observed in various cancers and is correlated with poor survival." (PMID 34178625, 2021). "There are many ways by which Notch signaling gets activated in cancer cells, and one of the Notch inducers is FGF1, which RFX1 negatively regulates." (PMID 33964962, 2021). "Summarizing, our data confirm the applicability of the FGF1-SA oligomers as highly effective drug delivery vehicles for the selective treatment of FGFR1-producing cancer cells." (PMID 34635096, 2021). "In BRAF/MEK inhibition-resistant cancer cells carrying BRAFV600E mutation, the dual MAPK inhibition drives the overexpression of FGF1 followed by the FGFR activation and the reactivation of ERK." (PMID 34830951, 2021). "Many factors derived by activated fibroblasts, such as MMP2 and fibroblast growth factor 1 (FGF1), can promote profound proliferation of cancer cells." (PMID 31167491, 2019). "More recently, an aberrant increase of IRES-dependent translation of key cancer gene mRNAs has been reported in cancer cells, including the major angiogenic factors FGF1, FGF2 and VEGFA, as well as c-myc and insulin growth factor-like receptor (IGF1R)." (PMID 30791615, 2019). "Based on the role of the FGF1–FGFR signaling axis in cancer, a number of novel drugs targeting this pathway have been developed and are recently undergoing preclinical and clinical trials in various FGFR-related tumors." (PMID 30134556, 2018). "There are two possible sources of FGF1 within epithelial cancers, namely, the cancer cells or surrounding stromal cells." (PMID 29632659, 2018). "Further studies on cancer cell lines continued in in vivo xenograft models will be essential to future development of generated anti-FGF1 molecules." (PMID 30134556, 2018). "Presented antibody fragments serve as novel FGF1 inhibitors and can be further utilized as powerful tools to use in the studies on the selective cancer therapy." (PMID 30134556, 2018).
cancer (continued). "More particularly, importin α1 bound directly to FGF1 and FGF2, secreted cNLS-containing growth factors, and addition of exogenous importin α1 enhanced the activation of ERK1/2, downstream targets of FGF1 signalling, in FGF1-stimulated cancer cells." (PMID 26887791, 2016). "The role of FGF1 and the molecular mechanisms by which FGF1-regulated EMT during cancer progression remain unsolved." (PMID 26334633, 2015). "FGF1 is a prototypic member of the FGF family, which has been implicated in a range of physiological processes, including development; wound healing and cancer development." (PMID 26334633, 2015). "Some FGFs, like FGF1 and FGF2, have potent angiogenic activity and are implicated as promoters of angiogenesis, the formation of new blood vessels, in cancer and chronic inflammatory diseases." (PMID 23469107, 2013). "We propose that R50E has potential as an anti-cancer and anti-angiogenesis therapeutic agent (“FGF1 decoy”)." (PMID 23469107, 2013). "Following incubation of frozen sections at 37 degrees C in phosphate-buffered saline, FGF1 staining was also revealed in myoepithelial cells and basement membrane adjacent to carcinoma cells." (PMID 9184178, 1997). "In the next step, we investigated whether honokiol could attenuate or nullify the protective effects of FGF1 on FGFR1-expressing cancer cells treated with the drug targeting tubulin polymerization, taltobulin." (PMID 39329123, 2024). "AKR1B10 may promote cancer progression through fatty acid synthesis, but prevent cancer via regulating autophagy and FGF1." (PMID 39712017, 2024). "Our study aimed to verify whether blocking FGF1/FGFR1 activity with honokiol or an FGF ligand trap is able to re-sensitize cancer cells to taltobulin and prevent the development of long-term drug resistance." (PMID 39329123, 2024). "Importantly, FGF1 expression was positively associated with ZEB1 and TWIST1 expression in pan-cancers." (PMID 35864158, 2022). "We further investigated whether FGF1 stimulation could suppress drug-induced apoptosis in cancer cells expressing FGFR1." (PMID 36276073, 2022). "This suggests that both canonical (PI3K-dependent) and alternative (PI3K-independent) AKT-activating pathways may regulate FGF1/FGFR1-driven cancer cell survival." (PMID 36276073, 2022). "Since targeting the FGF/FGFR axis might be promising for both regenerative medicine and cancer therapies, our findings highlight the complexity of the mechanism of FGF1’s protective action and the need for its further investigation." (PMID 35159330, 2022). "Accordingly, RES/FGF1 co-treatment could be developed as a new therapeutic strategy for improving outcomes in cancer patients receiving DOX." (PMID 36110535, 2022). "Taken together, RES could significantly resist FGF1-induced cancer cell proliferation, suggesting RES may be a nutritional replenishment as auxiliary therapy in the chemotherapeutic treatment of different types of cancer." (PMID 36235670, 2022). "Here, various cancer cells were applied to determine whether RES could antagonize the oncogenesis effect of FGF1." (PMID 36235670, 2022). "Finally, we wanted to clarify which signaling pathway(s) is responsible for the protective effect of FGF1 in cancer cells treated with taltobulin." (PMID 36276073, 2022). "Collectively, this study could provide a greater possibility for considering a combination of RES and FGF1 as a promising strategy in preventing anthracycline-induced heart disease and concomitantly synergizing with chemotherapy to delay cancer cell growth." (PMID 36235670, 2022). "Additionally, not only in the solid tissues, FGF1 expression was significantly lower in ccRCC cell lines comparing to other cancer cells." (PMID 33865387, 2021). "And the result showed that FGF1 loss expression in broad-spectrum ccRCC patients despite of the race, age, cancer grade and stage, and no significance relationship was found between FGF1 expression and patients gender." (PMID 33865387, 2021).
cancer (continued). "RFX1 can inhibit cell migration and invasion by repressing FGF1 in many cancers." (PMID 33964962, 2021). "Meanwhile, the immunohistochemistry (IHC) carried out in 104 local hospital ccRCC and paired normal renal tissues (different from the 30 samples used in qRT-PCR experiment) also revealed that FGF1 expression was significantly lower in cancer comparing to normal tissues." (PMID 33865387, 2021). "The secretion of FGF family members by CAFs has been shown in multiple different cancer settings: ovarian CAFs secrete FGF-1, leading to phosphorylation of the receptor, FGFR4; breast CAFs secrete FGF-2 and signal via both FGFR1 and FGFR2; and colon CAFs secrete FGF-1 and -3, and signal via FGFR4." (PMID 31861782, 2019). "Although the mutation of serine 780 in FGFR2 to leucine clearly increases FGFR2 tyrosine phosphorylation levels and FGF1-stimulated cell migration, the role of this mutation in cancer is not clear." (PMID 31146385, 2019). "We have previously reported that fibroblast growth factor 1 played pivotal roles in cancer development and generated a mouse scFv (mscFv1C9) could effectively prohibit cancer cell proliferation in vitro and in vivo." (PMID 29575613, 2018). "The development of FGF1-targeting molecules with potential implications for the therapy of FGF1-driven tumors is recently being considered a promising approach in the treatment of cancer." (PMID 30134556, 2018). "Furthermore, we found that the treatment with an anti-importin α1 antibody impaired FGF1 signalling, resulting in the suppression of cancer cell proliferation." (PMID 26887791, 2016). "The well-documented cancer-inducing ligands FGF1 and FGF9 are both highly expressed in Cepi." (PMID 23762861, 2013). "Therefore, having confirmed the inhibitory effect of honokiol on FGFR1 activity, we focused on determining whether honokiol could attenuate or abolish the protective activity of FGF1 in cancer cells exposed to taltobulin." (PMID 39329123, 2024). "Additionally, COX4I2 may be associated with fibroblast growth factor 1 (FGF-1), which plays pivotal roles in EMT, cancer-associated fibroblast activation, and angiogenesis." (PMID 39457539, 2024). "Additionally, these results suggest that FGF1-PIGN may be effective in the treatment of cancers expressing high levels of FGFR1." (PMID 38637316, 2024). "Thus, FGF1-PIGN may work inversely to wild-type FGF1 in cancer cells for which FGF1 is reported to promote proliferation and metastasis." (PMID 38637316, 2024). "However, the long term use of a wild-type FGF1, as a classically known mitogen, may enhance tumorigenic risks and increase the rate of metastasis owing to its strong mitogenic activity, which limits the use of FGF1 in clinic cancer-prone diseases." (PMID 36235670, 2022). "In this study, we determined that RES significantly decreased FGF1-induced cancer cell proliferation as well as unregulated apoptosis, suggesting RES, as an adjuvant drug, could effectively avoid the side effects of FGF1 application, especially in cancer-prone disease." (PMID 36235670, 2022). "In this study, we identified a set of associated DEGs (CD44, CTGF, DPP4, CRYAB, EGLN3, FGF1, and FOS) with at least one functional enrichment, such as “angiogenesis”, “binding of endothelial cells”, “development of blood vessel”, MAPK signaling, HCM, and pathways in cancer." (PMID 28623314, 2017). "However, FGF1 is unstable, and we had to express R50E in cancer cells for xenograft study, since injected R50E may rapidly disappear from circulation." (PMID 28302677, 2017). "We investigated whether the cell surface importin α1 affects FGF1 signalling in cancer cells." (PMID 26887791, 2016). "However, as FGF2 regulates neovascularization by increasing the expression of the glycolysis enzyme HK2 and by promoting the proliferation and migration of endothelial cells, FGF2 may synergize with FGF1 in controlling vascularization in the cancer microenvironment." (PMID 41131959, 2026).
cancer (continued). "Nevertheless, FGF1's natural involvement in cell migration, differentiation, growth, and survival raises concerns that its therapeutic administration could disrupt natural homeostasis, potentially promoting the development of diseases coexisting with T2D, such as cancer." (PMID 41520078, 2026). "Interestingly, the angiogenic potential of FGF1 to stimulate vascularization within adipose tissue, contributing to its remodeling, as well as within cancer cells, suggests that FGF1 may control the cancer microenvironment by acting on both cancer cells and adipocytes." (PMID 41131959, 2026). "The anti-cancer effects of Amlexanox have been attributed to the inhibition of IKBKE and TBK1 but also to the inhibition of other proteins like FGF-1 and S100 proteins." (PMID 40468448, 2025). "FGFBP1 has been reported to bind FGF1 and FGF2 and enhance biological activities in carcinoma cells." (PMID 40685360, 2025). "In A549 LC cells, fibroblast growth factor 1 (FGF1) -induced p-FGFR1 activated MMP26, which hence lead to cancer invasion, besides, inhibition of JNK significantly decreased the activation of MMP26 in response to FGF1 stimulation." (PMID 37766868, 2023). "Previously, we demonstrated the efficacy of fibroblast growth factor 1 (FGF1) and 2 (FGF2) as a targeting molecules for FGFR1-overproducing cancer cells." (PMID 37373291, 2023). "RCC tissues that successfully generated organoids highly expressed genes associated with stemness (WNT6/11, FZD8/9 and JAG2), cell matrix (MMP2, COL1A1), fatty metabolism (ACOT2, LIPE) and cancer development (TGFB1, SMAD6/7, EGF and FGF1)." (PMID 35802820, 2022). "FGF1 increases matrix metalloproteinase-9 (MMP-9) in ENU1564 breast cancer via activating PI3K/AKT pathway, eventually promoting cancer metastasis." (PMID 33964962, 2021). "In cancer, RFX1 promotes differentiation of CSCs by directly and indirectly targeting major stemness regulators like c-Myc, FGF1, and CD44." (PMID 33964962, 2021). "FGF1 and FGF2 can be overexpressed by cancer cells and have been correlated with advanced tumour stage." (PMID 33918004, 2021). "This study also measured the FGF-1 and TGF-β1 concentration after PAM treatment, in an attempt to determine why PAM can selectively damage CL1–5 cancer cells." (PMID 33097755, 2020). "BaF3-FGFR1 cells respond well to FGF1 stimulation (similarly to NIH/3T3) and are therefore a good model of FGFR-overexpressing cancers for in vitro proliferation assays." (PMID 30134556, 2018). "FGF2 is a molecule significantly more stable than FGF1, and binds to FGFR1, FGFR3 and, to a lesser extent, to FGFR2, allowing it to be a targeting molecule for a large group of FGFR-overexpressing cancers." (PMID 30029518, 2018). "Recently, both FGF1 and TAGLN have been identified as highly correlated cancer biomarkers in a cross‐tissue analysis of gene expression in cancer tissues." (PMID 28510269, 2017). "Mesenchyme-derived growth factors known to promote cancer cell proliferation (EGF, FGF1, FGF2, and IGF-1) were expressed in different CAF populations to different levels." (PMID 28649646, 2017). "In particular, the naphthalene compound 5-amino-2-naphthalenesulfonate, has been reported to inhibit both FGF1 and FGF227, a property whose pro and cons are still debated in view of the redundancy and promiscuity of the FGF/FGFR system in cancer." (PMID 27000667, 2016). "Next, we examined the effects of adding growth factors HGF, FGF1, FGF7, and FGF10, to the culture medium of cancer cells." (PMID 25884729, 2015). "FGF1/FGFR1 signaling (both autocrine and paracrine loops) thus plays a critical role in cancer progression." (PMID 23469107, 2013).
cancer (continued). "By comparing the effects of growth factor treatment on the control and SORL1 knockdown cell lines, we identified that SORL1 was involved in the cancer cell growth stimulated by CXCL12, BDNF, FGF1, and EGF1 in OVCAR8 cells and by BDNF, FGF1, and EGF1 in KRCH31 cells." (PMID 39858026, 2025). "Our results shed light on how blocking the FGF1/FGFR1 axis by honokiol and FGF ligand trap could help develop more effective cancer therapies, potentially preventing the emergence of drug-resistant relapses." (PMID 39329123, 2024). "By understanding the different t actions of FGF1 and EGF on individual cancer cell types, targeted approaches should become possible to develop new effective treatment approaches while preventing the acquisition of drug resistance and cancer progression." (PMID 37509496, 2023). "Overall, depletion of STYK1 from cancer cells may diminish persistence mechanisms elicited by EGFR inhibition, such as FGF1 upregulation, and in that way reduce/eliminate the pool of drug tolerant cells in which constitutive, genomic resistance may arise." (PMID 35840561, 2022). "As cancer cells secrete FGFs, we transfected NPC cells with an FGF1 overexpression plasmid or empty vector to determine whether FGF1 promotes NPC progression in an autocrine/paracrine secretion manner." (PMID 35864158, 2022). "Interestingly, inhibition of the mTOR pathway, but not the PI3K pathway, in triple-negative breast cancer cells led to increased FGF1 and Notch1 expression, enhanced FGFR1 activation and the formation of a resistant cancer stem cell-like population." (PMID 34830951, 2021). "FGF1 activation is mediated via the PI3K-Akt signaling pathway that lies upstream of mTOR, which is related to autophagy, apoptosis and metabolism of cancer cells, as well as the NLRP3-mediated inflammatory response." (PMID 32615540, 2020). "In FGF1-stimulated cancer cells, KPNA2 was found a role of bounding to FGF1 and FGF2, and the activation of ERK1/2 was increased through ectopic expression of importin α1, finally accelerating the cancer cell proliferation." (PMID 27611951, 2016). "Immunohistochemical analysis indicated that FGF-1 was present in the luminal epithelial cells of the non-malignant breast but was absent from cancer cells." (PMID 8519654, 1995). "Therefore, we assume the selective cytotoxicity of PAM to cancer cells is not through its effect on FGF-1 secretion." (PMID 33097755, 2020). "Therefore, FGF1‐dependent potential regulation of GLUT levels in several cell types, including epithelial cancer cells, may contribute to the reciprocal regulation of signaling and metabolism in the context of human cancer." (PMID 41131959, 2026). "The OD-BRE-0438 model with the most resistant phenotype, as evidenced by the shortest median PFS, showed statistically significant upregulated gene expression of FGF1, FGF7, and FGF8 ligands in cancer cells, while FGFR1, FGFR2, or FGFR3 were not upregulated." (PMID 40227585, 2025). "The action of FGFs, particularly FGF1 and FGF2, has been correlated with chemoresistance in many types of cancer, but the exact mechanisms have not been fully described." (PMID 36276073, 2022). "Similar results were obtained from breast cell lines in which 80% of cancer cell lines had very low levels of FGF-1, whereas all non-malignant breast cell lines contained higher levels of FGF-1." (PMID 8519654, 1995). "We believe that R50E may not induce such mutations in FGFR because R50E and FGF1 bind to FGFR exactly the same way, and blocking binding of FGF1 (and other members of the FGF family) to FGFR would not benefit cancer cells." (PMID 23469107, 2013).